BDNF (brain derived neurotrophic factor)
Diseases named in the same sentence as BDNF in open-access papers (continued):
Sharing a sentence is not in itself a finding about the gene and the disease.
status epilepticus (continued). "The objective of this study was to identify the signaling pathway that is immediately triggered by status epilepticus (SE) and in turn contributes to the excessive brain‐derived neurotrophic factor (BDNF)/tropomyosin‐related kinase receptor B (TrkB) signaling within the hippocampus." (PMID 32913950, 2020). "However, only the antisense strategy was effective in vivo, after inoculation in the hippocampus in a model of status epilepticus in which BDNF mRNA levels are strongly increased." (PMID 26954758, 2016). "Moreover, supplementation of BDNF attenuates astrocytosis and IL-1β expression after status epilepticus." (PMID 21949812, 2011). "Thus, we used a Herpes-based vector to supplement FGF-2 and BDNF in rat hippocampus after pilocarpine-induced status epilepticus that established an epileptogenic lesion." (PMID 21087489, 2010). "In a study, BDNF and FGF-2 induced a rapid attenuation of astrocytosis and microgliosis and prevented the IL-1β overexpression that is typical of the post-status epilepticus period." (PMID 38673746, 2024). "While PGE2 and brain-derived neurotrophic factor (BDNF) were highly expressed in the rat hippocampal formation after partial-status epilepticus, this was not the case following generalised-status epilepticus." (PMID 36291442, 2022).
colorectal cancer (28 papers, 2011 to 2026). A primary or metastatic malignant neoplasm that affects the colon or rectum. "In the present study, we investigated the association between the BDNF rs6265 polymorphism and PN symptoms in 393 female breast and colorectal cancer survivors." (PMID 37462904, 2024). "Mice living in the enriched housing environment showed less tumor growth and more frequent remission in melanoma and colorectal cancer, caused by elevated serum brain-derived neurotrophic factor (BDNF) and markedly lower leptin concentrations." (PMID 33117814, 2020). "Serum BDNF concentrations were measured with standard enzyme-linked immunosorbent assays, before and on the third day after the operation, in 50 consecutive patients with colorectal cancer and 25 patients with pancreatic cancer (tumours in the head of pancreas)." (PMID 34395067, 2021). "BDNF concentrations before and after the operation in patients with colorectal cancer, patients with pancreatic cancer, and the control group." (PMID 34395067, 2021). "In the current study, we investigated serum BDNF concentrations in patients that underwent surgical treatment for colorectal cancer or pancreatic cancer." (PMID 34395067, 2021). "The present study is aimed at examining the serum levels of brain-derived neurotrophic factor (BDNF) and investigating its role in differential diagnosis of colorectal cancer (CRC)." (PMID 33628340, 2021). "Here we demonstrated that CGI hypermethylation of FIGN, HTRA3, BDNF, HCN4 and STAC2 in colorectal cancer is associated with patient progression to metastasis, identifying them as putative future biomarkers for CRC progression." (PMID 32971738, 2020). "Sortilin as a neurotrophin transporter is implicated in cell proliferation and anti-apoptotic effect of Brain-Derived Neurotrophic Factor (BDNF) in colorectal cancer cell." (PMID 31908734, 2019). "As preserving the survival of several populations of central neurons, brain-derived neurotrophic factor (BDNF) now has been discovered with much higher expression level in colorectal carcinoma tissues." (PMID 28418861, 2017). "We sought to examine the clinical relevance of BDNF/TrkB expression in colorectal cancer (CRC) tissues, its prognostic value for CRC patients, and its therapeutic potential in vitro and in vivo." (PMID 24801982, 2014). "Brain-derived neurotrophic factor (BDNF) has been observed to be elevated in solid tumors including colorectal cancer." (PMID 24255678, 2013). "MicroRNA-497 has been reported to inhibit thyroid cancer tumor growth and invasion by suppressing BDNF, which is involved in cell proliferation and invasion of gastric cancer by repressing eIF4E, and to inhibit colorectal cancer growth by targeting insulin-like growth factor 1 receptor." (PMID 33015042, 2020). "BDNF/TrkB signaling may thus be a potential target for treating peritoneal carcinomatosis arising from colorectal cancer." (PMID 24801982, 2014). "In this study, we hypothesized that genetic variants located within the SLC6A4, BDNF, and AVPR1B genes are associated with prognosis in colorectal cancer patients." (PMID 22911682, 2012). "In colorectal cancer, SUN2 inhibited cell migration and invasion by decreasing the expression of brain-derived neurotrophic factor (BDNF) to inhibit the BDNF/TrkB signaling pathway." (PMID 36358787, 2022). "Emerging evidence demonstrates that CSCs isolated from gastric and colorectal cancers secrete neurotrophic factors such as nerve growth factor (NGF) and brain-derived neurotrophic factor (BDNF), which promote axonal growth and sympathetic/cholinergic marker expression in peripheral neurons." (PMID 41601691, 2026). "Moreover, some studies reported that METTL14 represses colorectal cancer (CRC) development via the PI3K/Akt signaling, upregulated by brain-derived neurotrophic factor (BDNF), which revealed similar evidence with our GO results." (PMID 38453794, 2024).
colorectal cancer (continued). "BDNF has been observed to be elevated in non-nervous system solid tumors including colorectal cancer." (PMID 24255678, 2013). "To distinguish between low and high BDNF expression related to survival with sufficient contrast and statistical power, we then determined whether BDNF was expressed in a larger dataset (TCGA-COAD) derived from 197 patients with colorectal cancer." (PMID 34771682, 2021). "In addition, the hypermethylation of FIGN, HTRA3, BDNF, HCN4 and STAC2 could be utilised in primary tumour as biomarkers of colorectal cancer prognosis." (PMID 32971738, 2020). "Statistical association between poor survival and hypermethylation of CGI was established in FIGN (p = 0.030), HTRA3 (p = 0.009), BDNF (p = 0.002), HCN4 (p = 0.018) and STAC2 (p = 0.007) and may be used as potential markers for metastasis progression in colorectal cancer." (PMID 32971738, 2020). "Consequently, in the present study, we have aimed to test the associations of five genetic variations in stress response genes (SLC6A4, BDNF, and AVPR1B) with clinical outcomes in a population-based cohort of 280 colorectal cancer patients from Newfoundland and Labrador (NL)." (PMID 22911682, 2012).
delirium (28 papers, 2012 to 2026). A disorder characterized by confusion; inattentiveness; disorientation; illusions; hallucinations; agitation; and in some instances autonomic nervous system overactivity. "This study examined the relationship between perioperative BDNF concentrations, the Val66Met polymorphism, and postoperative delirium (POD) incidence in patients undergoing isolated coronary artery bypass grafting (CABG)." (PMID 41227085, 2025). "The aim of this study is to investigate the impact of circulating BDNF concentrations and the BDNF Val66Met polymorphism on the occurrence of postoperative delirium in patients undergoing cardiac surgery with cardiopulmonary bypass." (PMID 41227085, 2025). "Reduced BDNF concentrations have been associated with impaired neuronal recovery and increased susceptibility to neurocognitive disorders, including delirium." (PMID 41227085, 2025). "For example, anaesthetic drugs and surgery have been linked with acute delirium and subsequent long-term deficits in cognition in older persons; effects associated with low levels of BDNF." (PMID 36564723, 2022). "The present study, to our knowledge, is the first study to investigate BDNF levels in delirium in older medical inpatients and explore the association with recovery of delirium." (PMID 28280733, 2017). "This prospective single-center study of patients undergoing isolated coronary artery bypass grafting (CABG) did not demonstrate a significant association between perioperative changes in BDNF concentrations or presence of the BDNF Val66Met gene mutation and the incidence of postoperative delirium." (PMID 41227085, 2025). "Accordingly, BDNF might be expected to worsen or precipitate delirium by potentiating dopamine activity; however, evidence shows that lower BDNF levels are associated with reduced delirium recovery and higher risk of postoperative delirium occurrence." (PMID 35955546, 2022). "The data suggest that neuropsychiatric syndromes (i.e., delirium) after peripheral trauma might be at least in part due to the activation of the hippocampal CRH/NF-κB/BDNF pathway, which results in a dramatic loss of synaptic contacts." (PMID 32051550, 2021). "Lower BDNF levels were clearly linked to delirium in oncology patients." (PMID 31263968, 2019). "Given that BDNF is a neurotrophic factor it might be expected that the occurrence of delirium would if anything be linked to lower levels." (PMID 28280733, 2017). "Therefore, the aims of the present study were (a) to investigate the relation of BDNF to the occurrence of delirium (both incidence and prevalence) and (b) the association of BDNF levels along with other relevant factors in the recovery of delirium." (PMID 28280733, 2017). "In addition, the results from the present study indicate that lower initial levels of BDNF together with higher MoCA scores are associated with a reduced frequency of delirium recovery." (PMID 28280733, 2017). "Carriers of the Met allele may be more vulnerable to memory disturbances and neuroinflammatory responses, especially under surgical stress; therefore, our findings suggest that BDNF Val66Met may represent a genetic determinant of susceptibility to postoperative delirium." (PMID 41227085, 2025). "For example, sevoflurane-induced associated extracellular vesicles can deliver miR-584-5p to promote the onset and progression of delirium by targeting BDNF to regulate Caspase3 and BDNF/TrkB signaling." (PMID 40661144, 2025). "BDNF has previously been proposed as a biomarker for postoperative delirium and postoperative cognitive dysfunction." (PMID 39060980, 2024). "BDNF mainly affects neuroplasticity and neurotransmission, and the reduced level increases the incidence of delirium." (PMID 37025488, 2023). "Most publications investigated the serum levels of BDNF in various ways, and only a few studies focused on the genetic basis of BDNF in the context of delirium." (PMID 37159618, 2023).
delirium (continued). "In aged patients, decreased serum levels of BDNF seem to correlate with postoperative delirium and POCD occurrence and interestingly, these serum levels also correlate with cerebrospinal fluid concentrations." (PMID 32066806, 2020). "This prospective, longitudinal study examined the relationship between BDNF levels and the occurrence of and recovery from delirium." (PMID 28280733, 2017). "The secondary outcomes were the relation between BDNF levels and delirium and coma-free days (DCFD) and ICU and hospital length of stay (LOS)." (PMID 23245494, 2012). "Future studies with larger cohorts and serial assessments of BDNF kinetics are warranted to clarify whether perioperative BDNF decline represents a contributing mechanism or merely an epiphenomenon in delirium pathogenesis." (PMID 41227085, 2025). "The findings suggest that BDNF might be a candidate for personalized medicine-based detection of delirium." (PMID 38928583, 2024). "Interestingly, BDNF also plays a role in postoperative delirium and postoperative cognitive dysfunction in elderly mice." (PMID 35845920, 2022). "Our data suggested that the decreased expression of the neuronal/synaptic plasticity related proteins PSD-95 and BDNF might be related to mitochondrial dysfunction and delirium-like behavior, which are induced by Surgery/Anesthesia." (PMID 31929114, 2020). "One study showed that greater decline in BDNF levels from baseline was associated with an increased incidence of delirium in patients undergoing spine surgery; POD vs no POD 75% vs 50%, p = 0.03." (PMID 30797230, 2019). "Excluding those who never developed delirium (n = 140), we examined the association of BDNF levels and other variables with delirium recovery." (PMID 28280733, 2017). "BDNF levels do not appear to be directly linked to the occurrence of delirium but recovery was less likely in those with continuously lower levels." (PMID 28280733, 2017). "The same study indicated that neuron-specific enolase and brain-derived neurotrophic factor (BDNF) could be potential biomarkers for delirium in intensive care unit patients." (PMID 26106326, 2015). "We demonstrated, in a case-control study, that BDNF was associated with delirium occurrence, but not with mortality, in this subgroup of patients." (PMID 23245494, 2012). "Therefore, it can be speculated that sevoflurane-induced POCD-associated exosomes delivered miR-584-5p may facilitate the occurrence and progression of delirium via targeting BDNF, and regulating Caspase 3 and BDNF/TrkB signaling." (PMID 36455873, 2022). "In oncology, a cross-sectional relationship has been established between blood BDNF and TNF-α levels with delirium." (PMID 38928583, 2024). "No previous study has investigated the role of BDNF in delirium recovery and these findings warrant replication in other populations." (PMID 28280733, 2017). "We demonstrate here that plasma levels of BDNF are related to mortality, independent of the presence of clinically detectable delirium, and to DCFD, but not to ICU and hospital LOS." (PMID 23245494, 2012). "Our key findings demonstrate that while neither BDNF levels nor the Val66Met polymorphism independently predicted POD, delirium occurred in 19.6% of patients and was strongly associated with adverse postoperative outcomes, including prolonged hospitalization, reoperations, and renal complications." (PMID 41227085, 2025). "Levels of BDNF did not have any significant effect on the occurrence of delirium." (PMID 28280733, 2017). "However, the percent decline in BDNF was more significant in patients who developed delirium than in those who did not, which suggests that plasma BDNF levels may be a biomarker for delirium." (PMID 38928583, 2024). "The observed trend toward lower BDNF levels in the DEL+ group, even in the absence of statistical significance, may therefore suggest a pathophysiological link between decreased neurotrophic support and the development of delirium." (PMID 41227085, 2025).
vascular dementia (28 papers, 2013 to 2025). A degenerative vascular disorder affecting the brain. "Therefore, the reduction of blood BDNF level is thought to be an early AD diagnostic biomarker and can be used to differentiate it from vascular dementia." (PMID 40380033, 2025). "A clinical study included patients with PD, AD, Lewy body dementia, vascular dementia and frontotemporal dementia and displayed that BDNF serum levels were dysregulated in those patients compared to healthy controls." (PMID 38006577, 2024). "BDNF serum level is increased in PD patients but reduced in patients with AD, Lewy body dementia, vascular dementia and frontotemporal dementia." (PMID 38006577, 2024). "This is in line with a previous study that showed that bee venom successfully recovered BDNF levels in a mouse model of vascular dementia." (PMID 35163115, 2022). "Gastrodin injection combined with hyperbaric oxygen in the treatment of vascular dementia patients can optimize cerebral hemodynamics and improve the level of serum brain-derived neurotrophic factor, which is a very effective combination therapy." (PMID 35463081, 2022). "NBP treatment also increased ChAT, AChE, VAChT, and BDNF expressions, suggesting that central cholinergic dysfunction is involved in vascular dementia pathogenesis and NBP is effective to protect the cholinergic system via activating the BDNF signaling." (PMID 34071978, 2021). "A recent study has shown that melatonin prevents hippocampal damage and cognitive dysfunction against BCCAO-induced vascular dementia by altering BDNF expression." (PMID 34804374, 2021). "Decreased plasma/serum BDNF levels have been previously reported only in different morphological types of vascular dementia." (PMID 27597800, 2016). "In the majority of neurodegenerative and vascular dementias a reduction of BDNF concentration in the brain and concurrently in plasma or serum has been reported." (PMID 27597800, 2016). "There are also suggestions that fluoxetine may increase BDNF concentration levels and improve cognitive functioning in vascular dementia, which may be due to upregulation of BDNF expression through stimulation of the serotonergic system." (PMID 34640441, 2021). "GAS targeting SIRT1/BDNF pathway may be a potential therapeutic target for vascular dementia." (PMID 35463081, 2022). "However, the severity of nervous tissue damage in manifest vascular dementia might sufficiently decrease the BDNF synthesis." (PMID 27597800, 2016). "Administration of donepezil has been found to protect against vascular dementia by inhibiting the nuclear translocation of histone deacetylase 6 (HDAC6) and the binding of HDAC6 to BDNF promoter IV, which enhances BDNF expression." (PMID 35090576, 2022). "In the present study, we compared serum BDNF in 624 subjects: 266 patients affected by AD, 28 by frontotemporal dementia (FTD), 40 by Lewy body dementia (LBD), 91 by vascular dementia (VAD), 30 by PD, and 169 controls." (PMID 24024214, 2013). "Thus, it is manifested that BDNF and NMDAR play an important role in synaptic plasticity and forming process of LTP in vascular dementia." (PMID 30405354, 2018). "Also, it has been reported that HSYA improves cognitive function in the rat model of vascular dementia via increasing VEGF and NR1, and enhancing the endogenous expression of BDNF and NMDARs in the hippocampus." (PMID 30405354, 2018).